HDAC2 (histone deacetylase 2)
Diseases named in the same sentence as HDAC2 in open-access papers (continued):
Sharing a sentence is not in itself a finding about the gene and the disease.
tumor (continued). "Besides, studies have shown that HDAC2 enhances the infiltration of tumor lymphocytes and inhibits IL6 through its histone deacetylation function." (PMID 34880761, 2021). "Importantly, recent studies have reported that the deacetylation of PD-L1 by HDAC2 triggers its nuclear accumulation, which facilitates the evasion of tumor cells from the immune surveillance during the metastatic process." (PMID 34365463, 2021). "The associations between HDAC1/HDAC2/HDAC3 and classical clinicopathological characteristics such as age, tumor size, histological grade, lymph node status, ER, PR, HER2, brain metastasis and molecular subtypes were analyzed by Spearman's rank‐correlation test and χ2 test." (PMID 32686908, 2020). "Additionally, there was an inverse relationship between the expression levels of miR-489-3p and HDAC2 in BC tumor tissues." (PMID 32774482, 2020). "Furthermore, the expression analysis demonstrated that HDAC2 was significantly upregulated in BC tumor tissues compared with corresponding normal tissues." (PMID 32774482, 2020). "Moreover, miR-489-3p overexpression-mediated in vivo xenograft tumor growth suppression was accompanied by a significant decrease in HDAC2." (PMID 32774482, 2020). "The tumor-promoting role of USP4 also relates with HDAC2 activation." (PMID 32669974, 2020). "The univariate results of Cox regression analysis showed that increased tumor size/histological grade/lymph node invasion/HDAC1/HDAC2/nuclear HDAC3/cytoplasmic HDAC3 were significantly associated with shorter overall survival, while positive ER or PR was associated with prolonged overall survival." (PMID 32686908, 2020). "Collectively, MAKV-8 appears to be an attractive drug candidate for further consideration in CML therapies, especially considering that the inhibition of HDAC1 and HDAC2, upregulated in LSCs versus HSCs from patients, strongly impacts the transcription of proteins essential for tumor cell survival." (PMID 32430012, 2020). "Besides, therapeutic delivery of miR-500a-5p significantly suppresses tumour development in a xenograft tumour model and a HDAC2 inhibitor FK228-treated CRC model." (PMID 30737378, 2019). "We identified that miR-500a-5p functions as a tumour suppressor, and we wondered whether this miRNA combined with HDAC2 inhibitor, FK228, induced apoptosis in CRC cells." (PMID 30737378, 2019). "HDAC2, its overexpression has a correlation with DNA-damage response and promote tumor progression." (PMID 30906311, 2019). "Notably, mice bearing HDAC2-C262A/C274A tumors had an increase in the number of tumor infiltrating lymphocytes (TILs), such as CD8+ T cells and macrophages, which were linked with the type I IFN pathway." (PMID 31805977, 2019). "Moreover, the LoVo/HDAC2 group rapidly proliferated and tumour vessel density increased compared with the LoVo/Vector and LoVo/miR-500a-5p cell groups, whereas LoVo/miR-500a-5p/HDAC2 inhibited the growth rate and tumour vessel density in the LoVo/HDAC2 group." (PMID 30737378, 2019). "Recent progress has highlighted the significance of HDAC2 in tumour progression." (PMID 30737378, 2019). "In this study, we report that TRPS1, USP4, and HDAC2 form a regulatory axis to confer tumor growth." (PMID 30071870, 2018). "Our observation that USP4 is recruited by TRPS1 to de-ubiquitinate HDAC2 and silence USP4, resulting in inhibition of tumor cell growth by TRPS1, is consistent with these notions elucidating the underlying molecular details of the oncogenic function of the TRPS1/HDAC2/USP4 axis in tumor growth." (PMID 30071870, 2018). "miR-145 also acts as a tumor suppressor by inhibition of HDAC2 in liver cancer." (PMID 28538837, 2017).
tumor (continued). "Furthermore, Hdac1 and Hdac2 function as tumor suppressors on preleukemic stage, but oncogenes for leukemia maintenance in PML-RAR-mediated mouse acute promyelocytic leukemia." (PMID 29126425, 2017). "Worth to note, CNAs of 37 genes were exclusively found in G3 tumours such as WNT7B (4 gains), BAD (3 gains), WEGFB (3 gains) and HDAC2 (3 losses) in respect to 65 CNA genes exclusively presented in G1 tumours, such as GRB2 (5 losses) and FGF21, STAT3, CTNNA3 and DVL3 with 3 losses each." (PMID 28486536, 2017). "Eμ-myc tumor development was significantly delayed in mice having a single allele of Hdac2 and no Hdac1 (Hdac1Δ/Δ; Hdac2Δ/+), while this was not the case in mice with a single allele of Hdac1 and no Hdac2 (Hdac1Δ/+; Hdac2Δ/Δ)." (PMID 27886239, 2016). "Interestingly, we observed that mono-allelic expression of Hdac2 in Hdac1-deficient Eμ-myc B cells (Hdac1Δ/Δ; Hdac2Δ/+) resulted in delayed tumor development, whereas complete Hdac1 and Hdac2 deletion (Hdac1Δ/Δ; Hdac2Δ/Δ) prevented tumorigenesis altogether." (PMID 27886239, 2016). "Therefore, we performed conditional targeted deletion of Hdac1 and Hdac2 in Eμ-myc tumor cells using an in vivo transplantation approach." (PMID 27886239, 2016). "However, several recent studies reported opposing tumor-suppressive or tumor-promoting roles for Hdac1 and Hdac2." (PMID 27886239, 2016). "Furthermore, a recent study also showed that ablation of both Hdac1 and Hdac2 decreases proliferation and induces apoptosis in Eμ-myc tumor cells." (PMID 27886239, 2016). "Eμ-myc mice with a single allele of Hdac2 and no Hdac1 (Hdac1Δ/Δ; Hdac2Δ/+), but not with a single allele of Hdac1 in absence of Hdac2 (Hdac1+/Δ; Hdac2Δ/Δ), exhibited delayed tumor development." (PMID 27886239, 2016). "Indeed, HDAC2 is considered a tumor promoting protein, with inhibition resulting in cell death, effectively reducing tumor growth." (PMID 26501324, 2015). "A previous report studying the effect of the HDACi depsipetide (FK228), which most potently inhibits all class I HDACs, demonstrated that the tumor most sensitive to depsipeptide treatment tested (a CNS-PNET) had the highest expression of HDAC2 relative to HDAC1, and 3-7." (PMID 25853389, 2015). "According to this model, complete loss of HDAC1 and HDAC2 is not compatible with cell proliferation, indicating that drugs inhibiting the activities of both enzymes have the potential of anti-tumor agents." (PMID 24449838, 2014). "A similar positive effect on cell proliferation by a single Hdac2 allele in the absence of HDAC1 in T cells was shown to favor tumor formation." (PMID 24449838, 2014). "The increased expression of anti-apoptotic genes, including EIF3H, RFFL and HDAC2, may favorably assist uncontrolled cell growth and proliferation to enhance tumor growth in patients with HCC-R." (PMID 24377043, 2013). "Most interestingly, we could find a significantly higher expression of HDAC2 and −3 in more aggressive tumor types." (PMID 23627572, 2013). "Our results show that the mRNA and protein levels of HDAC1 and HDAC2 were both decreased in the presence of wogonin, indicating that acetylated histone protein may promote expression of tumor suppressive proteins and thereby inhibit tumor progression." (PMID 24265759, 2013). "In addition, sustained suppression of HDAC2 attenuated in vitro colony formation and in vivo tumor growth in a mouse xenograft model." (PMID 22132221, 2011). "By stratifying patients for Gleason groups, we found that differences in relapse-free survival in dependence of HDAC2 expression were especially prominent in the subgroup of patients with Gleason 7 tumours (Gleason 2–6: P=0.833, Gleason 7: P=0.008, Gleason 8–10: P=0.272)." (PMID 18212746, 2008).
tumor (continued). "For HDACs with a broader deacetylation specificity than SIRT1, such as HDAC1 and HDAC2, no somatic mutations in tumours have been described, but a dysregulated expression seems to be a common feature of human neoplasia." (PMID 16404435, 2006). "However, HDAC2 can be reactivated, repressing tumor-suppressor gene expression, such as PHLDA1." (PMID 41224124, 2025). "Recent findings have shown that nuclear PD-L1, which is acetylated at K263 by p300 and deacetylated by HDAC2, acts as a transcription factor that alters gene expression related to antigen presentation and inflammatory pathways, affecting cytotoxic T lymphocyte activity and tumor immune evasion." (PMID 38654302, 2024). "If so, HDAC2 might mediate cellular interactions within the tumor microenvironment." (PMID 36968022, 2023). "Interestingly, HDAC-2 staining demonstrated an heterogenous pattern, varying between isolated clusters of tumor cells to multiple clusters and to widespread expression throughout the tumor, which was strongly correlated with IRS." (PMID 34638249, 2021). "Our data also suggest that Rack1 is not only essential for GNPs proliferation and migration at postnatal cerebellar developmental stage, which may also play an important role in enhancing SHH‐type MB tumor formation by positively regulating the expression and function of Gli1 and HDAC2." (PMID 34480519, 2021). "In addition, the tumor-promoter role of HDAC2 in BC was also validated." (PMID 32110804, 2020). "In addition, the mice injected with LoVo/HDAC2 cells developed larger tumours than those injected with LoVo/Vector and LoVo/miR-500a-5p cells, whereas the LoVo/miR-500a-5p/HDAC2 cells formed smaller xenograft tumours than did LoVo/HDAC2 cells." (PMID 30737378, 2019). "Similarly, HDAC2, a well-established tumor promoter, is also overexpressed in a majority of PDACs." (PMID 31500290, 2019). "Therefore, we used the biotin-switch assay to test whether NOS1 directly modifies HDAC2 by means of S-nitrosylation in tumor cells." (PMID 31805977, 2019). "Thus, HDAC2 appears to represent a therapeutic target, and the development of anticancer drugs specific for HDAC2 may inhibit tumor metastasis and prevent the side effects from the current pan-HDACi treatment." (PMID 31805977, 2019). "Hence, an effect on proliferation and apoptosis upon Hdac1 and Hdac2 ablation could likely explain the delayed tumor appearance in our transplantation experiment." (PMID 27886239, 2016). "Thus, Hdac1 and Hdac2 have a pro-oncogenic role in the Eμ-myc dependent tumor progression." (PMID 27886239, 2016). "Hence, HDAC2 expression in a given tumour might be of prognostic value and also predict the response to combinatorial (HDACis/drug) therapy." (PMID 27283986, 2016). "Therefore, we first investigated whether ablation of Hdac1 and Hdac2 in B cells also induces tumor development." (PMID 27886239, 2016). "HDAC2 overexpression may therefore play a crucial role in tumor immune escape." (PMID 25473896, 2015). "The overexpression of HDAC1, HDAC2, HDAC3, and HDAC6, together with aberrant DNA methylation, contributes to tumor suppressor gene silencing." (PMID 41562705, 2026). "Recent research has elucidated that HDAC2, a member of the class I HDAC family, can impact tumor immune evasion by catalyzing the acetylation of PD‐L1, thus influencing its nuclear translocation." (PMID 41267925, 2025). "It targets histone deacetylase 2 (HDAC2) for degradation, which in turn activates the interferon‐induced protein with tetratricopeptide repeats (IFIT) family, effectively hindering tumor growth and promoting apoptosis." (PMID 39928532, 2025). "Systemic administration of HDACi delayed or completely abrogated tumor development, whereas T cell-specific depletion of HDAC1 or HDAC2 or inactivation of the catalytic activity of HDAC1 significantly accelerated lymphomagenesis." (PMID 40175628, 2025).
tumor (continued). "The results demonstrated that HDAC2 overexpression promoted tumor growth and compromised cisplatin-induced growth inhibition, and treatment with the HDAC inhibitor Entinostat reversed HDAC2-mediated cisplatin resistance." (PMID 41408324, 2025). "Regarding cisplatin treatment, HDAC2 upregulation also significantly impaired cisplatin-induced tumor growth inhibition, while the combination of the HDAC inhibitor Entinostat with cisplatin reversed the cisplatin resistance induced by HDAC2 overexpression." (PMID 41408324, 2025). "The downregulated HDAC2, in turn, restrains the transcription of PJA2, forming a feedback loop that enhances the tumor‐inhibitory effect of PJA2." (PMID 39928532, 2025). "In CRC tissues, the upregulated HDAC2 due to the reduction of PJA2 restrains the transcription of PJA2 and forms a feedback loop to aggravate tumor progression." (PMID 39928532, 2025). "Our findings underscore the tumor-suppressive function of HDAC1 and HDAC2 in T cells during ALCL development." (PMID 40175628, 2025). "Blocking the binding of HDAC2 to the promoter of HIF-1α can activate the transcription of HIF-1α, which can promote tumor growth and metastasis." (PMID 39876842, 2024). "Our results indicate that inhibition of HDAC2 expression significantly mitigates the malignant behavior of HCC and suppresses tumor growth, along with reduced autophagy levels." (PMID 39147759, 2024). "In our comprehensive analysis of HDACs in DLBCL patients using public databases, we found that the expression levels of HDAC1, HDAC2, HDAC3, HDAC6, HDAC7, HDAC8, and HDAC9 were higher in tumor tissues compared to normal control for the first time." (PMID 38168914, 2024). "In contrast, DNMT3a-TET2 crosstalk silences tumor suppressors (i.e., P15, SOCS2) through a corepressor complex with HDAC2 along with increased promoter DNA methylation." (PMID 38528605, 2024). "As valproate has been considered an HDAC2 inhibitor, we investigated the role of TAGLN in tumor cell response by rescuing treatment effects with TAGLN overexpression (TAGLN‐OE) in GSCs." (PMID 38087889, 2024). "This strongly supports our first observation that HDAC2 is positively and HDAC7 is negatively correlated with tumor stemness." (PMID 39063083, 2024). "Depending on its expression level, HDAC2 can positively or negatively control the transcriptional activity of CIITA and B2M, which, in turn, can be differently regulated within the tumor microenvironment." (PMID 37046620, 2023). "We explored tumor-infiltrating immune cells in COAD tumors from the TCGA cohort with different SCNAs in CIITA, HDAC2, and B2M." (PMID 37046620, 2023). "Recently, CUDC-907 has been demonstrated to inhibit both HDAC1 and HDAC2 as well as PI3K, Akt and mTOR expression and this resulted in an inhibition of NB tumor growth in a 3D spheroid tumor model." (PMID 37679770, 2023). "Thus, the combination of HDAC2 inhibitor and PD-1/PD-L1 immunotherapy is hypothesized as a novel tumor treatment strategy with great clinical application and research prospects, which provides a new opportunity to further improve the overall prognosis of patients with HCC." (PMID 37716965, 2023). "This study reports that GATA1- and HDAC2-mediated NRBP2 downregulation induced TME and angiogenesis in TC cells in vitro and tumor growth and macrophage infiltration in vivo." (PMID 35491849, 2022). "In conclusion, this study reports that GATA1 can recruit HDAC2 to the NRBP2 promoter to induce its transcriptional suppression, which leads to M2 polarization of macrophages and tumor angiogenesis and development." (PMID 35491849, 2022). "HDAC1 and HDAC2 were relatively upregulated whereas HDAC11 was downregulated in LGG and GBM tumor tissues." (PMID 35359455, 2022).
tumor (continued). "Statistical analysis showed that the high‐HDAC1 expression group had worse nodal status (P = 0.003) and advanced tumor node metastasis (TNM) stage (P = 0.01); the high‐HDAC2 expression group had more patients with liver invasion (P = 0.03)." (PMID 35075805, 2022). "In summary, we suppose that HDAC2 regulates the expression of BUB1B in NPC to participate in the occurrence and progression of tumor." (PMID 36577966, 2022). "The upregulation of HDAC2 and PHOX2B accelerated tumorigenesis and enhanced tumor volume after 28 days." (PMID 35060363, 2022). "HDAC1 and HDAC2 were relatively upregulated and HDAC11 was downregulated in LGG and GBM tumor tissues." (PMID 35359455, 2022). "Whereas HDAC1 and HDAC2 promote UC, HDAC5 is often downregulated and only weakly expressed in UC cell lines, suggesting a tumor-suppressive function." (PMID 35624179, 2022). "Patients with a higher percentage of tumor cells positively immune-stained for HDAC1 and HDAC2 expressions were more likely to experience shorter disease-free survival, as well as higher T and N stages, and triple-negative pathology." (PMID 34580286, 2021). "For instance, HDAC2 degrades CIITA to antagonize its activity and promotes the expression of MHC-II, highlighting its important role in the anti-tumor reactivity." (PMID 34365463, 2021). "HBx was shown to interact with HDAC1 and HDAC2, and HBx-induced stabilization of hypoxia-inducible factor 1 alpha (HIF-1α), a key regulator in tumor growth, angiogenesis and metastasis of HCC, involved deacetylation by HDAC1." (PMID 34361112, 2021). "As mentioned in the introduction, HDAC2 is one of the main targets of HBI-8000, providing further evidence that HDAC2 plays a role in the induction of tumor immunity in the tumor microenvironment." (PMID 35070972, 2021). "HDAC2 was highly co-expressed with MDM2, and pharmacological HDAC2 inhibition decreased MDM2 expression and enhanced tumor cell apoptosis." (PMID 35008848, 2021). "We performed immunofluorescence assay (IFA) with two MDV lymphoblastoid tumor cell lines, MSB-1 and MKT-1, using antibodies against Meq and HDAC1 or HDAC2." (PMID 33437016, 2021). "High HDAC-2 and HDAC-6 expression levels were more frequently observed in malignant thyroid tumors, with HDAC -1, -4 and -6 being correlated with tumor size." (PMID 34441281, 2021). "On the other hand, HDAC1, HDAC2, and HDAC3 expression was increased in HBV-positive HCCs, in HBx-expressing cells, and in the liver of HBx transgenic mice compared to matching non-tumor tissue, control liver cells, and wild-type mice, respectively." (PMID 34361112, 2021). "We found that the expression of both Gli1 and HDAC2 was significantly upregulated in SHH‐MB tumors compared to WT cerebellum, indicating the over activation of SHH signaling in SHH‐MB tumor cells." (PMID 34480519, 2021). "HDAC2 is co-expressed with MDM2, and HDAC2 inhibition results in decreased MDM2 expression and enhanced tumor cell apoptosis." (PMID 35008848, 2021). "For clarification of HDAC2-pivoted mechanism in ESCC, we tested HDAC2 expression in 121 cases of ESCC tumor and mucosal tissues, as well as in ESCC cell lines and HEEC by RT-qPCR and Western blot assay." (PMID 33926524, 2021). "Next, to assess the effect of HDAC2 on the tumor growth, the mammary fat pad injection was performed in BALB/c mice with WT and HDAC2-KO cells, and the growth was also monitored by IVIS system." (PMID 34365463, 2021). "To investigate the function of the NuRD complex on the genome level, we performed ChIP-seq assays in RH4 cells for CHD4, RBBP4, HDAC2, and MTA2, as well as for the tumor driver P3F, and other relevant epigenetic regulators and histone marks." (PMID 32744500, 2020).